CD44 (CD44 molecule (IN blood group))
Diseases named in the same sentence as CD44 in open-access papers (continued):
Sharing a sentence is not in itself a finding about the gene and the disease.
breast carcinoma (continued). "In an analysis of 466 invasive breast carcinomas and eight breast cancer cell lines, basal-like breast cancer harbored the highest percentage of tumor cells with the CSC phenotype CD44+CD24−/low and ALDH1 positivity." (PMID 31505803, 2019). "The frequency of breast cancer CTCs as indicated by CD44+CD24− was also significantly increased from PDX tumors with obASCs." (PMID 31118047, 2019). "It was found that 500-kDa HA stimulated ABCB1 expression via CD44 in breast cancer (MCF-7 cells), inducing resistance to doxorubicin, paclitaxel, and etoposide." (PMID 31443261, 2019). "Augmented CD44 and VEGF in breast cancer cells are associated with OSX‐mediated cell migration and angiogenesis." (PMID 30450809, 2019). "CD44-ICD was shown to regulate the expression of several genes through its interaction with RUNX2 in breast cancer cells." (PMID 31331331, 2019). "In this study, we enriched breast cancer stem cells with CD44+/CD24- from MDA-MB-231 and HCC1806 cells through magnetic-activated cell sorting and cultured these in serum-free medium." (PMID 31612865, 2019). "Inhibitors and knock-down strategies showed that the JAK/STAT3 pathway regulates CPT1 and FAO, and thereby self-renewal in breast cancer CD44+/CD24− mammosphere TICs." (PMID 31661927, 2019). "The expression level of CD44, a marker of breast cancer stem cells, was significantly increased in 4T1_L_3R cells compared to parental 4T1-3R cells." (PMID 31717306, 2019). "In this unusual particulate form, both types of protein materials selectively penetrate and kill CD44+ tumor cells in culture, and upon local administration, promote destruction of tumoral tissue in orthotropic mouse models of human breast cancer." (PMID 31559131, 2019). "The surface expression of CD44+/high CD24−/low cells has been considered a stem population marker of breast cancers or cell lines." (PMID 31533776, 2019). "A subpopulation of breast cancer CTCs marked with EpCAM+CD44+CD47+MET+ was enriched with metastasis-initiating capacity and associated with a reduction in overall survival." (PMID 30934773, 2019). "DLG5 silencing decreased the sensitivity to TAM and increased the frequency and stemness of CD44+/CD24− breast cancer stem cells (BCSCs) and TAZ, a transducer of the Hippo pathway, expression in MCF7 cells while DLG5 overexpression had opposite effects." (PMID 30450766, 2019). "Our study uncovers a new mechanism for csGRP78 to regulate behaviors of tamoxifen-resistant breast cancer cells at least in part via modulating CD44 protein expression." (PMID 31416894, 2019). "As a natural ligand for CD44 that is often over-expressed in breast cancer cells, HA can also effectively mediate breast cancer-targeted drug delivery." (PMID 31623608, 2019). "It is now known that breast cancer stem cells exist in distinct mesenchymal-like (epithelial–mesenchymal transition [EMT]) as CD44+/CD24− and epithelial-like (mesenchymal-epithelial transition [MET]) states that express ALDH1." (PMID 31261917, 2019). "T-DM1 resistance resulted in increased cell surface levels of ROR1 along with CSC-like properties, such as higher percentages of ALDH1+ and CD44+ in ROR1+/T-DM1-resistant breast cancer cells." (PMID 31382410, 2019). "CD44-overexpressing breast cancer stem cells and a bulk breast cancer cell were chosen to evaluate, in vivo and in vitro, the redox responsive release." (PMID 31311150, 2019). "To evaluate the effect of Gomisin M2 on BCSCs, we first analyzed the activity of Gomisin M2 against the breast cancer stem cells (with the CD44+/CD24- biomarkers) in MDA-MB-231 and HCC1806 cells." (PMID 31612865, 2019). "In contrast with several above-mentioned MPs (e.g., CD44, EGFR/ERBB2, and APP) that have been well studied, the interacting partners and pathways associated with CHRNA9 in breast cancer remain to be elucidated." (PMID 31311925, 2019).
breast carcinoma (continued). "In breast cancer, it was shown that the tumorigenic potential was lost by inhibiting the transition from CD44-low toward CD44-high cells." (PMID 30992437, 2019). "It has been shown that the HER2+CD44+CD24−/lo subpopulation of breast cancer cells displays high ALDH activity, in vivo tumorigenic potential, and radioresistance." (PMID 30733805, 2019). "Recent studies have shown that CD44 knockdown increases the sensitivity to anticancer drugs in breast cancer cells, myeloma, and colon cancer." (PMID 31497537, 2019). "Breast Cancer Stem Cells (BCSCs) were initially described in 2003 by Al-Hajj and colleagues, who found that the CD44+CD24−/lowLin− fraction was significantly enriched for cells with tumor forming ability as compared to the CD44+CD24+Lin− population." (PMID 31619007, 2019). "As a result of CD44 cleavage, CD44 itself is one of the genes that can be transcribed as well as MMP-9 in breast cancer cells." (PMID 31331331, 2019). "The murine CD44+ CD24− cancer stem cell population found in the primary tumors of MMTV-PyMT transgenic mice exhibits functional characteristics of human breast cancer stem cells, which highlights the clinical impact of our finding." (PMID 31555258, 2019). "For instance, breast cancers after neoadjuvant chemotherapy are enriched from CD44+CD24− CSCs that also express mesenchymal markers." (PMID 31417869, 2019). "CSCs were first identified in leukemia in 1994, and in solid tumors they were first demonstrated in the CD44+CD24−/low fraction of breast cancer." (PMID 31013960, 2019). "The NF-kB inhibition and subsequent CD44 suppression reduced the cell proliferation and invasiveness of breast cancer cells." (PMID 31731625, 2019). "Elimination of hnRNPM prevents TGFβ induced breast cancer metastasis in mice by decreasing the mesenchymal-related standard CD44 isoform." (PMID 31666932, 2019). "Consistently, the gene expression profile of CD44+CD24−/low breast cancer cells more closely resembles that of CD44+CD24−/low cells from normal breast tissue." (PMID 30959764, 2019). "Recent studies showed that CD44+CD24- cell population (breast cancer stem cell subpopulation) in MCF-7 cells were resistant to tamoxifen treatment, however, tamoxifen resistant cells harbored higher number of CD44+CD24- cell population than MCF-7 cells." (PMID 31120927, 2019). "The percentage of CD44+CD24− cells is higher in basal-type compared with luminal-type breast cancer; therefore, attempts to target CSCs have mainly focused on the basal subtype." (PMID 31137841, 2019). "Breast cancer TICs with the canonical CD44+/CD24-/EpCAM+ signature showed massive upregulation of FA biosynthesis enzymes FASN, ACLY, ACC1 and the master regulator SREBP1." (PMID 31661927, 2019). "The expression levels of breast cancer stem cell markers, such as CD44 and Nanog33,43,44, as well as the expression levels of Jagged-1 and Hes1, were increased in BMP-4-treated MDA-MB-231 cells, compared to control cells." (PMID 31409851, 2019). "In order to confirm the association of LSD1 with breast cancer stem cells, we performed immunohistochemistry for LSD1 and CD44 in a small set (n = 10) of tissue sections from patients with invasive triple-negative breast cancer (TNBC)." (PMID 31627418, 2019). "We found that miR‐200c was weakly expressed in both breast cancer cells and CD44+CD24− phenotype stem cells." (PMID 31599500, 2019). "HA (Hialuronic Acid)-SPIONs conjugated with anti-CD44 (Cluster of Differentiation 44) antibodies have been investigated in a breast cancer model." (PMID 30791358, 2019). "It has already been shown that breast cancer cells with the CD44+CD24−/low phenotype that overexpress aldehyde dehydrogenase 1 (ALDH1+) are able to form tumors in mice with high tumorigenic capacity." (PMID 31261917, 2019). "The repressed expression of CD44 and NF-κβ genes in the present study pointed towards the existence of a similar kind of probabilistic mechanism in Lf treated breast cancer cells." (PMID 31847364, 2019).
breast carcinoma (continued). "In solid tumors, the presence of CSCs was first demonstrated in the CD44+CD24−/low fraction of breast cancer cells." (PMID 31013960, 2019). "Inhibition of HA synthesis or, at higher extent, depletion of CD44, decreases the stem-like properties of basal-type breast cancer cells." (PMID 31159154, 2019). "Increasing evidence suggests that a key downstream signalling axis that contributes to TGFβ-induced invasion and metastasis of breast cancer is the hyaluronan (HA)-cluster of differentiation 44 (CD44) pathway." (PMID 31361756, 2019). "Studies by others have identified CD44 cleavage product (CD44-ICD) in complex with RUNX2 on the promoter of the MMP-9 gene in breast cancer cells." (PMID 31331331, 2019). "To investigate the transcriptional variability of CD44high cells, we carried out sorting driven, scRNA-seq of CD44-GFP luminal breast cancer cells." (PMID 31477698, 2019). "Pyrvinium pamoate, an anthelmintic drug and inhibitor of the Wnt/β-catenin pathway, prevented the proliferation of breast cancer cells, especially CD44+CD24−/low and ALDH+ CSCs, via downregulating NANOG, OCT4, and SOX2." (PMID 31137841, 2019). "CD44 targeting reduces tumor growth and prevents post-chemotherapy relapse of human breast cancer xenografts." (PMID 30899759, 2019). "This is in agreement with previous findings showing that the mesenchymal-like breast cancer stem cells are characterized as CD24−/CD44+, while the epithelial-like breast cancer stem cells express high levels of aldehyde dehydrogenase (ALDH)." (PMID 31261917, 2019). "HA, which is elevated in different carcinomas including breast cancer stroma and blood serum acts as a ligand for CD44." (PMID 31361756, 2019). "In contrast, luminal and HER2+ breast cancer subtypes are thought to be ALDH+ (CD44+CD24low/−ALDH1+)." (PMID 31450577, 2019). "Increased ALDH activity and CD44 (CD44hi/CD24low) expression have been identified as some of the key markers for breast cancer stemness." (PMID 31867270, 2019). "Circulating tumor cell (CTC) analysis in our PDX model revealed a significant increase in human circulating cells (HLA1+) enriched for breast cancer stem cell marker (CD44+CD24−)." (PMID 31118047, 2019). "ETC inhibitors also target glycolytic CSCs, such as CD44+CD24low cells in breast cancer or SP cells in nasopharyngeal carcinoma, highlighting the importance of ETC for coupled ATP production, avoiding electron loss in the form of ROS." (PMID 30967773, 2019). "NF-κβ strongly affects the proliferation and invasiveness of breast cancer cells by regulating CD44 expression." (PMID 31847364, 2019). "Other studies in breast cancer also have shown cleavage of CD44 intracellular domain to be responsible for activation of stemness factors that promote tumorigenesis." (PMID 31331331, 2019). "In a breast cancer study, CSCs isolated from patients’ tumors identified as a CD44+ population expressed significantly higher levels of OSF-2 in comparison to the CD44- population." (PMID 31412536, 2019). "In breast cancer, a subpopulation of cells that displayed stem cell properties was identified and characterized by cell surface markers CD44 expression and are thus called “breast cancer stem cells” (BCSCs)." (PMID 31007609, 2019). "In this study, we defined these markers and CD44+/CD24low as BCSC-associated markers and employed these biomarkers to label stem cells among patients with early stage breast cancer." (PMID 31340763, 2019). "Given this knowledge, researches began genetically profiling CD44+ breast cancer tumor cells and identified a CD44+ cell-specific gene, Protein C receptor (PROCR)." (PMID 31379741, 2019). "We found that miR‐200c was down‐regulated in both breast cancer cell lines and CD44+CD24− phenotype breast cancer cell line stem cells." (PMID 31599500, 2019). "ALDH1- CD44+ Ki67- CSCs, shown within mammary tumors and located in a peripheral position, at the invasive front, would be presumable CSC3s, constituting about 12.87% of the tumor mass." (PMID 30899759, 2019).
breast carcinoma (continued). "Although the CD44+/CD24−/low markers have been widely used to identify breast cancer cells with stemness properties, there are controversies regarding their tumorigenicity." (PMID 30200262, 2018). "BMP-2 also promoted the formation of tumor spheroids and increased the population of CD44+/CD24− cells in MCF-7 breast cancer cells." (PMID 29339728, 2018). "The cellular uptake for Apt1-Liposome (Lip) was tested among two CD44 (+) cell lines, human lung cancer cells (A549), and human breast cancer cells (MDA-MB-231) compared to CD44 (−) cell line, mouse embryonic fibroblast cells (NIH/3T3)." (PMID 29747682, 2018). "CD44 alternative splicing was differentially regulated in a murine model of breast cancer progression, resulting in a shift in expression from CD44v to CD44s during the development of recurrent mesenchymal type of breast tumors." (PMID 29747682, 2018). "These included important oncogenic signaling proteins such as epidermal growth factor receptor, as well as the breast cancer stem cell marker CD44." (PMID 29892572, 2018). "The CD44+/CD24- tumor cell fraction is increased in breast cancer patients upon administration of neoadjuvant chemotherapy." (PMID 29455658, 2018). "Invasive potential of breast cancer cells with a mesenchymal phenotype can be inhibited by rat anti-human CD44-specific antibodies (IM7)." (PMID 29747682, 2018). "The functional role of CD44 on cancer cell metabolism was evaluated by knock-down of CD44 via retroviral delivery of shRNA against CD44 in human breast cancer cells." (PMID 29747682, 2018). "For instance, CD44 is significantly expressed by breast cancer cells, where it promotes invasion and adhesion to BM, and breast CSCs were initially identified as CD44+CD24− cells." (PMID 29461491, 2018). "In a HER2-overexpressing breast cancer cell line, resistant to trastuzumab, the breast cancer-initiating CD44+/CD24-/low population was more sensitive to MTF treatment than the non-CD44+/CD24-/low population (estimated IC50 for MTF 1 ± 0.2 mM vs. 11 ± 2 mM)." (PMID 30241339, 2018). "To evaluate the function of IBC in the paclitaxel resistance phenotypes of ERα+ breast cancer cells, we detected the protein expression of ERα and CD44 in paclitaxel‐resistant breast cancer cells with IBC treatment." (PMID 30179299, 2018). "This difference suggests that the regulatory mechanism of CD44 expression differs between gastric cancer cells and basal‐like breast cancer cells." (PMID 29356399, 2018). "This was consistent with our previous findings and strongly suggested that ERα expression was significantly positively correlated with CD44 expression in paclitaxel‐resistant breast cancer cells." (PMID 30179299, 2018). "A luciferase reporter assay demonstrated that miR-143 directly targeted the 3′-UTR of CD44 in breast cancer cells." (PMID 29747682, 2018). "Mucin-4 and CD44 are the cell surface proteins overexpressed in trastuzumab resistant breast cancer patients." (PMID 29455658, 2018). "Overall, this is the first study demonstrating that BMP-2 is a driving factor for promoting EMT and breast cancer stemness via Rb and CD44 signaling pathways." (PMID 29339728, 2018). "MCF10A cells were sorted for a population of CD24− or low/CD44+ tumor-initiating cells because this subtype represents tumor-initiating properties in breast cancer." (PMID 30486409, 2018). "Silencing of CD44 in human breast cancer cell lines suppressed activation of a signaling axis involving c-Src/AKT/LKB1/AMPKɑ/HIF-1ɑ." (PMID 29747682, 2018). "Taken together, for the first time, our results demonstrated that inhibition of ERα by IBC can down‐regulate CD44 expression and thus decrease paclitaxel resistance in ER+ breast cancer cells and xenograft tumour models." (PMID 30179299, 2018). "The effect of Foxp3 on regulation of the CD44 promoter activity in breast cancer cells was assessed by ChIP and EMSA analysis." (PMID 29747682, 2018).
breast carcinoma (continued). "CD44+/CD24- or aldehyde dehydrogenase 1 (ALDH1) has been suggested as a potential marker for breast cancer stem cells." (PMID 29416796, 2018). "Although putative breast cancer stem cells have been suggested to express the CD44+/CD24- marker combination, CD24 alone has been implicated in the regulation of tumor growth and metastasis in previous studies." (PMID 29416796, 2018). "The previously reported inhibition of CD44 expression in breast cancer cells by calcitriol analogue BXL0124 can be blocked by downregulation of VDR, suggesting that the VDR plays a critical role in the regulation of CSC population by calcitriol." (PMID 29581858, 2018). "The DiD+ population displayed only partial overlap with the CD44+CD24−/low cell surface protein marker signature widely used to identify breast cancer stem cells, but was enriched for CD44+CD24+ cells." (PMID 30377878, 2018). "In breast cancer tissues, AR and let-7a expression were correlated with the phenotype of CD44+/CD24-/low." (PMID 29423076, 2018). "Several distinct CD44 isoforms co-precipitated with MMP-9 in mouse mammary carcinoma and human melanoma cells and this interaction is believed to help localize MMP-9 to the cell surface." (PMID 29747682, 2018). "Enhanced lung metastasis has been reported upon SMAR1 knockdown in breast cancers by an increased alternative splicing of CD44." (PMID 29765542, 2018). "Sims-Mourtada and co-workers co-treated breast cancer cells with Hh inhibitors and docetaxel and found a decrease in the CD44+/CD24− BCSC population and mammosphere formation that was on the contrary increased when treating with docetaxel alone." (PMID 30200262, 2018). "Significant coexpression of the H2 antigen (CD173) and the Lewisy antigen (CD174) with the cancer stem cell marker CD44 has been identified in breast cancer tissue sections and in breast cancer cell lines." (PMID 29527514, 2018). "To identify the isoform regulated by KHDRBS3 in basal‐like breast cancer, we performed reverse transcription PCR with forward and reverse primers for CD44 designed at exon 5 and 15, respectively." (PMID 29356399, 2018). "CD44, a key cancer stem cell (CSC) marker, was downregulated in trastuzumab-resistant breast cancer and associated with the trastuzumab resistance in GC." (PMID 30134903, 2018). "They showed that a subset of breast cancer cells expressing CD44+CD24−/low were tumorigenic with as few as 102 cells capable of initiating tumor growth in NOD/SCID mice." (PMID 29671772, 2018). "Originally, breast cancer stem cells (BCSCs) were defined by their expression of Cluster of Differentiation (CD) CD44 and CD24 (CD44+/CD24−/low), and subsequent studies have provided more detailed insights into the molecular nature of the BCSCs." (PMID 30388742, 2018). "In the current work, we developed novel nanoparticles of hyaluronan-polypyrrole nanorods (HA-FeOOH@PPy NRs) for PAI-guided PTT to target CD44 positive breast cancer cells." (PMID 29891947, 2018). "Among individual transcripts identified by this analysis were several genes known to be associated with the metastatic process (ALCAM, MALAT1) and EMT (SNAI1, GSC, FOXC2, SIP1) and breast cancer stem cells (CD44)." (PMID 29291741, 2018). "Clinical evidence showed a positive correlation between CD44 expression and breast cancer bone metastasis." (PMID 29747682, 2018). "To study the roles of ERα and CD44 in the acquisition of resistance to anticancer agents, we selected ERα+ breast cancer cells to establish drug‐resistant cell models." (PMID 30179299, 2018). "The parental BT474 cells were almost exclusively CD24+/CD44-, which is characteristic of luminal breast cancer." (PMID 29879129, 2018). "In this study, we showed that CD44+/CD24–/low BCSCs enriched from HER2-negative breast cancer cells displayed a radioresistant phenotype with HER2 and EGFR overexpression." (PMID 29464036, 2018).